SPRR2B (small proline rich protein 2B)
Description:
Cross-linked envelope protein of keratinocytes. It is a keratinocyte protein that first appears in the cell cytosol, but ultimately becomes cross-linked to membrane proteins by transglutaminase. All that results in the formation of an insoluble envelope beneath the plasma membrane.
Tractability: Antibody: its Gene Ontology location is reachable by antibodies, with high confidence.
Gene: Protein-coding gene on chromosome 1 (153,070,226 to 153,071,611, reverse strand). Ensembl gene ENSG00000196805.
Subcellular location: Cytoplasm
Pathways (Reactome):
Developmental Biology: Formation of the cornified envelope
Gene Ontology:
Biological process: epidermis development; keratinocyte differentiation
Cellular component: cornified envelope; cytosol; cytoplasm
Genetic constraint (gnomAD): Loss-of-function variants: 3 observed, 1.95 expected, observed/expected ratio (o/e) 1.54, 90% interval 0.57 to 1.93. That is too few expected variants to judge how well the gene tolerates losing a copy. Missense variants: 52 observed, 79.98 expected, observed/expected ratio (o/e) 0.65, 90% interval 0.52 to 0.82. Synonymous variants: 27 observed, 27.38 expected, observed/expected ratio (o/e) 0.99, 90% interval 0.73 to 1.36.
Homologues: Orthologues: chimpanzee SPRR2B (100% identical). Paralogues in human: SPRR2D (97% identical), SPRR2E (97% identical).
Diseases named in the same sentence as SPRR2B in open-access papers:
SPRR2B is named in the same sentence as 18 diseases in open-access papers, as found by Europe PMC text mining. Sharing a sentence is not in itself a finding about the gene and the disease. The quoted sentences say what the papers report.
gastric cancer (3 papers, 2022 to 2024). A primary or metastatic malignant neoplasm involving the stomach. "Previous studies have found that SPRR2B is highly expressed in gastric cancer and is an independent predictor of the poor prognosis of gastric cancer." (PMID 38152044, 2024).
asthma (2 papers, 2011 to 2021). "While the roles of SPRR1B and SPRR3 in asthma are unclear, it has been shown that the members of the SPRRs family SPRR2A and SPRR2B are upregulated in an IL-13-dependent manner in an allergen-induced asthma model." (PMID 35126350, 2021). "SPRR2A and SPRR2B were found to be increased in ovalbumin and an Aspergillus fumigatus-induced asthma model." (PMID 35126350, 2021). "Our investigation revealed that six of these genes (PDE4B, SPRR2B, ADCY2, KIF3A, DNAH5, and PLAU) were located in chromosomal regions that had been previously linked to asthma or other allergic disease phenotypes and had been shown to be regulated during allergic inflammation." (PMID 21912604, 2011).
melanoma (2 papers, 2021 to 2023). A malignant, usually aggressive tumor composed of atypical, neoplastic melanocytes. "Overall, this systematic meta-analysis of gene profiling was a step forward in the investigation of the mechanisms underlying melanoma's metastasis, and the role of SPRR1B, SPRR2B, TGM1, CDSN, and IVL in keratinocyte differentiation GO term needs to be further studied." (PMID 35003328, 2021). "But the report of SPRR1B, SPRR2B, TGM1, CDSN, and IVL in melanoma was a gap." (PMID 35003328, 2021).
psoriasis (2 papers, 2016 to 2022). An autoimmune condition characterized by red, well-delineated plaques with silvery scales that are usually on the extensor surfaces and scalp. "The expression of many genes known to be associated with psoriasis, including Lce3f, Sprr2b, Krt15, S100a8, S100a9, Il17a, Il17f, Il18, Il20, Il22, and Ccl20, was downregulated in the skin of IMQ-treated Camk4−/− mice compared with those of IMQ-treated Camk4+/+ mice." (PMID 35869084, 2022).
gastric adenocarcinoma (1 paper, 2022).
cancer (2 papers, 2022 to 2024). A tumor composed of atypical neoplastic, often pleomorphic cells that invade other tissues. "Within the family of small proline-rich proteins (SPRR), SPRR2B and other members like SPRR2E are of particular interest in oncology due to their roles in cancer progression." (PMID 39000413, 2024). "Moreover, the approach has also emphasized the importance of the small proline-rich protein family (SPRR), including SPRR2B, SPRR2E, and SPRR2D, recognized for their significant involvement in cancer-related pathways and their potential as therapeutic targets." (PMID 39000413, 2024). "Additionally, the GLMQL-MAS system highlighted the small proline-rich protein family (SPRR) including SPRR2B, SPRR2E, and SPRR2D, noted for their significant roles in cancer-related pathways and their potential as therapeutic targets." (PMID 39000413, 2024).
SPRR2B also shares sentences with these, for which no sentence is quoted: metastatic melanoma (2 papers); allergic disease (1); childhood asthma (1); colorectal cancer (1); dermatitis (1); eczema (1); ichthyosis (1); laryngeal carcinoma (1); Palmoplantar keratoderma (1); Pruritus (1); skin disorder (1); tumor (1).